TMEM105 (TMEM105 long non-coding RNA)
Synonyms: FLJ38792
Gene: Long non-coding RNA gene on chromosome 17 (81,311,270 to 81,330,674, reverse strand). Ensembl gene ENSG00000185332.
Subcellular location: Membrane
Diseases named in the same sentence as TMEM105 in open-access papers:
TMEM105 is named in the same sentence as 11 diseases in open-access papers, as found by Europe PMC text mining. Sharing a sentence is not in itself a finding about the gene and the disease. The quoted sentences say what the papers report.
breast carcinoma (4 papers, 2023 to 2025). "The area under the ROC curve (AUC) was 0.803 (95% CI = 0.777–0.830), indicating a high diagnostic value of TMEM105 expression in breast cancer." (PMID 36737428, 2023). "Here, the expression of TMEM105 associated with glycolysis was dramatically elevated from normal to breast cancer to breast cancer liver metastasis tissues, and the survival analysis revealed that high TMEM105 expression was related to poor survival, especially in patients with liver metastasis." (PMID 36737428, 2023). "Furthermore, we observed that lactate level was associated with the upregulation of TMEM105, and 5 mM of lactate was enough to dramatically induce the TMEM105 expression in breast cancer cells." (PMID 36737428, 2023). "It was reported that the lncRNA TMEM105 played an important role in promoting breast cancer growth and metastasis by regulating tumor glycolysis." (PMID 40083702, 2025). "In breast cancer, lactate upregulates transmembrane protein 105 (TMEM105), which in turn promotes glycolysis and LDHA-mediated lactate generation, establishing a positive feedback loop that facilitates liver metastasis." (PMID 41152975, 2025). "TMEM105 was a lncRNA that plays a role in promoting breast cancer growth and metastasis by regulating tumor glycolysis function in breast cancer liver metastasis." (PMID 40083702, 2025). "It suggested that TMEM105 enhanced the migration and invasion of breast cancer cells in an LDHA-dependent manner." (PMID 36737428, 2023). "The overall survival (OS) time was shorter in TMEM105 high expressing breast cancer patients by survival analysis." (PMID 36737428, 2023). "Univariate and multivariate Cox proportional hazards analyses revealed that TMEM105 expression was an independent prognostic factor for OS in breast cancer patients in the Hebei dataset." (PMID 36737428, 2023). "Here, TMEM105 was significantly upregulated in breast cancer tissues, facilitating glycolysis and promoting BCLM." (PMID 36737428, 2023). "The results revealed that the injection of TMEM105-overexpressing or knockdown breast cancer cells promoted or suppressed the human genomic DNA in the livers, and these effects were reversed after cotransfection with miR-1208 mimics or inhibitors." (PMID 36737428, 2023). "Our results revealed that TMEM105 expression was increased from adjacent normal tissues to breast cancer to the paired BCLM." (PMID 36737428, 2023). "As a sponge of miR-1208, TMEM105 upregulated LDHA expression by competitively interacting with miR-1208 in breast cancer cells thereby promoting glycolysis and BCLM." (PMID 36737428, 2023). "To further validate the findings from the analysis of the public datasets, we detected the expression of TMEM105 by qRT-PCR in the specimens from breast cancer patients collected in our institution." (PMID 36737428, 2023). "To further confirm the epigenetic effect of TMEM105 on miR-1208 in vivo, we injected breast cancer cells into the spleen of nude mice." (PMID 36737428, 2023). "The results showed that the TMEM105 expression in breast cancer cells was significantly higher compared to MCF10A cells." (PMID 36737428, 2023). "In the present study, we identified that TMEM105 expression was dramatically increased from normal to breast cancer to breast cancer liver metastasis tissues, and high TMEM105 expression was related to poor survival, especially in patients with liver metastases." (PMID 36737428, 2023). "We further transfected miR-1208 mimics into TMEM105-overexpressing breast cancer cells or transfected miR-1208 inhibitors into TMEM105-knockdown breast cancer cells, which attenuated the effects of TMEM105 overexpression or knockdown on wound healing, respectively." (PMID 36737428, 2023). "Importantly, glycolytic production of lactate enhanced TMEM105 expression in breast cancer cells by activating the SHH-MAZ signaling pathway." (PMID 36737428, 2023).
breast carcinoma (continued). "Based on these findings, we addressed whether TMEM105 promoted glycolysis in breast cancer cells by sponging miR-1208." (PMID 36737428, 2023). "In addition, breast cancer cells transfected with miR-1208 mimics or miR-1208 inhibitors were able to completely reverse the effect of TMEM105 overexpression or knockdown on OS time in the mice." (PMID 36737428, 2023). "Additionally, quantitative analysis of LDHA expression in breast cancer samples showed that LDHA expression was positively related to TMEM105 expression, particularly in BCLM tissues." (PMID 36737428, 2023). "Importantly, the TCGA dataset indicated that breast cancer patients with high TMEM105 expression had poor OS." (PMID 36737428, 2023). "The aberrant activation of LDHA by TMEM105 might be the result of the metabolic adaptation for the survival of breast cancer cells in the cancer microenvironment." (PMID 36737428, 2023). "To evaluate whether these predicted candidate miRNAs are interacting with TMEM105, we constructed a luciferase reporter vector containing the wild type of TMEM105 (Luc-TMEM105-WT) and cotransfected it with miRNA mimics into the breast cancer cells." (PMID 36737428, 2023). "Moreover, TMEM105 facilitated the glycolysis of breast cancer cells and induced cell invasion and breast cancer liver metastasis (BCLM)." (PMID 36737428, 2023). "We further examined the role of LDHA in TMEM105-mediated metastasis of breast cancer cells." (PMID 36737428, 2023). "Furthermore, we evaluated the expression of TMEM105 in breast cancer cells and normal breast epithelial cell MCF10A." (PMID 36737428, 2023). "Thus, TMEM105 played an important role in the progression of breast cancer, especially during BCLM." (PMID 36737428, 2023). "To clarify whether TMEM105 could be used as a predictor of metastasis, we defined patients in the TCGA dataset according to the occurrence of distant metastasis, and the results showed that TMEM105 significantly predicted breast cancer metastasis using ROC curve analysis (AUC = 0.640)." (PMID 36737428, 2023). "Additionally, we prepared three truncated mutants of TMEM105 promoter, with truncated mutations at position 1 (Promoter-MUT1-Luc), position 2 (Promoter-MUT2-Luc) or both positions (Promoter-MUT3-Luc), and cloned them into pGL3 vector and transfected them into breast cancer cells." (PMID 36737428, 2023). "Among the breast cancer cells, TMEM105 expression was lower in MCF-7/T47D and higher in MDA-MB-231/BT549 cells, so these cell lines were used to prepare TMEM105 overexpression or knockdown cells for further studies." (PMID 36737428, 2023). "To clarify the potential function of TMEM105, we performed gene set enrichment analysis (GSEA) on the data of breast cancer patients in the TCGA dataset." (PMID 36737428, 2023). "ISH analysis showed that TMEM105 expression was slightly increased in breast cancer tissues without BCLM, but intensely upregulated in BCLM tissues." (PMID 36737428, 2023).
lobular carcinoma (2 papers, 2022 to 2023). "The lncRNA TMEM105, a ferroptosis and immune-related lncRNA, serves as prognostic and diagnostic biomarker for patients with breast-infiltrating duct and lobular carcinoma." (PMID 36923215, 2023). "The expression of AC078883.1 and ADAMTS9-AS1 were significantly decreased, while the expression of the AL035661.1, CBR3-AS1, FTX, and TMEM105 were significantly increased in the patient with breast infiltrating duct and lobular carcinoma with high-risk value." (PMID 35444943, 2022). "Finally, we found that AC007686.3, AC078883.1, ADAMTS9-AS1, AL035661.1, CBR3-AS1, FTX, and TMEM105 were significantly associated with the OS of patients with breast infiltrating duct and lobular carcinoma." (PMID 35444943, 2022). "We found that seven ferroptosis- and immune-related differentially expressed lncRNAs (FI-DELs) (AC007686.3, AC078883.1, ADAMTS9-AS1, AL035661.1, CBR3-AS1, FTX, and TMEM105) were correlated with the overall survival of patients with breast infiltrating duct and lobular carcinoma." (PMID 35444943, 2022).
bladder urothelial carcinoma (1 paper, 2023). "Furthermore, analysis of the TCGA dataset showed that TMEM105 was notably overexpressed in several types of human cancers, such as bladder urothelial carcinoma, esophageal carcinoma, and many other types of cancers." (PMID 36737428, 2023).
celiac disease (1 paper, 2019). An autoimmune genetic disorder with an unknown pattern of inheritance that primarily affects the digestive tract. "On the other hand, the top non-HLA DMRs in celiac disease mapped to genes related to the immune response, including NLRC5 and TMEM105 in the epithelial fraction, and CAST and HOXC4 in the immune compartment." (PMID 30718669, 2019).
coronary artery disease (1 paper, 2025). "TMEM105 was also believed to play a crucial role in coronary artery disease." (PMID 40083702, 2025). "In addition, TMEM105 was believed to play a crucial role in coronary artery disease." (PMID 40083702, 2025).
gastric adenocarcinoma (1 paper, 2021). "We have reasons to infer that ncRNA FLJ22447 and lncRNA TMEM105 were carcinogenic ncRNA in gastric adenocarcinoma." (PMID 34790582, 2021). "The results suggested that TMEM105, PVT1, FLJ22447, DLEU1, and LOC646588 closely related to the prognoses of patients with gastric adenocarcinoma." (PMID 34790582, 2021).
pancreatic cancer (1 paper, 2025). "Take it to conclude, TMEM105 mitigates the pancreatic cancer disulfidptosis through combining with β-catenin." (PMID 40083702, 2025). "In this experiment, stimulating β-catenin in TMEM105-knockdown cells led to the suppression of disulfidptosis and the restoration of proliferation and metastatic capabilities of pancreatic cancer cells." (PMID 40083702, 2025). "In this study, TMEM105 was found to promote pancreatic cancer progression in vivo and in vitro, and mitigate disulfidptosis of PCa in vitro." (PMID 40083702, 2025). "In addition, Ki-67 staining and TUNEL staining confirmed that TMEM105 knockdown inhibited pancreatic cancer cell proliferation and induced cell apoptosis in vivo." (PMID 40083702, 2025). "It was found that TMEM105 was predominantly located in the nucleus of pancreatic cancer cells." (PMID 40083702, 2025). "In conclusion, TMEM105 regulates pancreatic cancer growth and disulfidptosis through β-catenin." (PMID 40083702, 2025). "Consequently, lymph node metastasis, tumor differentiation, and TMEM105 expression were identified to impact the prognosis of pancreatic cancer significantly by univariate COX regression analysis." (PMID 40083702, 2025). "Hence, we hypothesized that TMEM105 may exert its regulatory effects on pancreatic cancer progression and disulfidptosis through interacting with β-catenin." (PMID 40083702, 2025).
tumor (4 papers, 2021 to 2025). "Intriguingly, oral administration of BAY-876 restored the augmentation of tumor weight and volume caused by TMEM105 overexpression." (PMID 40083702, 2025). "It was revealed there was a significant reduction in term of both volume and weight of the tumor components following TMEM105 downregulation compared to the control group." (PMID 40083702, 2025). "It was found that there was significantly higher expression level of TMEM105 in PCa tumor tissues compared to adjacent normal tissues." (PMID 40083702, 2025). "Mechanically, TMEM105 engages a β-catenin-c-MYC-GLUT1 cascade to promote tumor growth and antagonize disulfidptosis in PCa." (PMID 40083702, 2025). "Additionally, Ki-67 staining and TUNEL assays respectively indicated that TMEM105 overexpression promoted tumor proliferation and inhibited tumor apoptosis, while inhibition of GLUT1 reversed this effect." (PMID 40083702, 2025). "In addition, ncRNA FLJ22447 and lncRNA TMEM105 were upregulated in tumor tissues versus normal tissues, and their hazard ratio was greater than 1, which was mainly highly expressed in the high-risk group and clusters representing the high-risk group." (PMID 34790582, 2021). "Thus, we speculated that TMEM105 may regulate the tumor progression and disulfidptosis in PCa through GLUT1." (PMID 40083702, 2025).
cancer (3 papers, 2022 to 2023). A tumor composed of atypical neoplastic, often pleomorphic cells that invade other tissues. "Moreover, high TMEM105 expression was associated with cancer metastasis and poor prognosis, which suggested that TMEM105 might have a carcinogenic role in the progression and development of human cancers." (PMID 36737428, 2023). "Unfortunately, there is no literature information about the potential role and significance of TMEM105 lncRNA (TMEM105 long non-coding RNA) in cancer immunology, and it is difficult to discuss the observed results for HNSCC patients." (PMID 36294833, 2022). "It indicated that TMEM105 expression was higher in cancer tissues with BCLM than in the cancer tissues without BCLM." (PMID 36737428, 2023). "For AC007686.3, AC078883.1, and TMEM105, although there were no reported relationships between them and cancer at present, our research suggested that they were closely related to BRCA cancer." (PMID 35444943, 2022).
TMEM105 also shares sentences with these, for which no sentence is quoted: esophageal carcinoma (1 paper); lymph node metastasis (1).